LRP6 (LDL receptor related protein 6)
Description:
Component of the Wnt-Fzd-LRP5-LRP6 complex that triggers beta-catenin signaling through inducing aggregation of receptor-ligand complexes into ribosome-sized signalosomes. Cell-surface coreceptor of Wnt/beta-catenin signaling, which plays a pivotal role in various processes including retinal angiogenesis and bone formation. The Wnt-induced Fzd/LRP6 coreceptor complex recruits DVL1 polymers to the plasma membrane which, in turn, recruits the AXIN1/GSK3B-complex to the cell surface promoting the formation of signalosomes and inhibiting AXIN1/GSK3-mediated phosphorylation and destruction of beta-catenin. Required for posterior patterning of the epiblast during gastrulation (By similarity).
Synonyms: ADCAD2; EVR8; OPTA4; STHAG7
Tractability: Small molecule: a structure with a bound ligand is known; a high-quality ligand is known; it has a high-quality binding pocket. Antibody: UniProt places it where antibodies can reach, with high confidence; its Gene Ontology location is reachable by antibodies, with high confidence; UniProt predicts a signal peptide or a membrane-spanning region. PROTAC: UniProt records ubiquitination sites on it; ubiquitination databases record sites on it; its protein half-life has been measured; a small molecule that binds it is known.
Gene: Protein-coding gene on chromosome 12 (12,116,025 to 12,267,185, reverse strand). Ensembl gene ENSG00000070018.
Subcellular location: Cell membrane; Endoplasmic reticulum; Membrane raft
Pathways (Reactome):
Signal Transduction: Disassembly of the destruction complex and recruitment of AXIN to the membrane; Negative regulation of TCF-dependent signaling by WNT ligand antagonists; Regulation of FZD by ubiquitination; TCF dependent signaling in response to WNT
Disease: Signaling by RNF43 mutants
Gene Ontology:
Molecular function: coreceptor activity; frizzled binding; identical protein binding; kinase inhibitor activity; low-density lipoprotein particle receptor activity; protein binding; protein homodimerization activity; protein serine/threonine kinase inhibitor activity; signaling receptor binding; toxin transmembrane transporter activity; Wnt receptor activity; Wnt-protein binding
Biological process: canonical Wnt signaling pathway; cellular response to cholesterol; negative regulation of smooth muscle cell apoptotic process; neural crest cell differentiation; neural crest formation; positive regulation of cell cycle; positive regulation of DNA-templated transcription; positive regulation of transcription by RNA polymerase II; protein localization to plasma membrane; Wnt signaling pathway; dopaminergic neuron differentiation; midbrain dopaminergic neuron differentiation; nervous system development; anatomical structure formation involved in morphogenesis; cell-cell adhesion; chemical synaptic transmission; chordate embryonic development; midbrain development; positive regulation of cytosolic calcium ion concentration; regulation of apoptotic process; regulation of DNA-templated transcription; response to peptide hormone; tissue development; transmembrane transport; vesicle-mediated transport
Cellular component: caveola; cell surface; cytoplasmic vesicle; early endosome; Golgi apparatus; membrane raft; plasma membrane; Wnt signalosome; Wnt-Frizzled-LRP5/6 complex; early endosome membrane; extracellular region; endoplasmic reticulum; neuronal cell body; synapse
Genetic constraint (gnomAD): Loss-of-function variants: 35 observed, 172.06 expected, observed/expected ratio (o/e) 0.2, 90% interval 0.15 to 0.27. The upper end of that interval is the gene's LOEUF score, 0.27, which puts it in group 1 of 6, group 1 being the genes least tolerant of losing a copy. Missense variants: 1,457 observed, 1,977.1 expected, observed/expected ratio (o/e) 0.74, 90% interval 0.7 to 0.77. Synonymous variants: 675 observed, 685.26 expected, observed/expected ratio (o/e) 0.99, 90% interval 0.92 to 1.05.
Homologues: Orthologues: chimpanzee LRP6 (99% identical), macaque LRP6 (99% identical), dog LRP6 (99% identical), guinea pig LRP6 (99% identical), pig LRP6 (99% identical), rabbit LRP6 (99% identical), rat Lrp6 (98% identical), mouse Lrp6 (98% identical), tropical clawed frog lrp6 (86% identical), zebrafish lrp6 (48% identical), Drosophila melanogaster arr (44% identical). Paralogues in human: LRP5 (70% identical), LRP4 (38% identical), LRP1 (30% identical), LRP1B (29% identical), LRP2 (27% identical), LRP8 (12% identical), VLDLR (12% identical), EGF (11% identical), NID1 (9% identical), NID2 (8% identical), LRP3 (5% identical), and 2 more.
Diseases named in the same sentence as LRP6 in open-access papers:
LRP6 is named in the same sentence as 189 diseases in open-access papers, as found by Europe PMC text mining. Sharing a sentence is not in itself a finding about the gene and the disease. The quoted sentences say what the papers report.
breast cancer (77 papers, 2009 to 2026). A primary or metastatic malignant neoplasm involving the breast. "This is consistent with the studies that show LRP6 is associated with metastasis and poor prognosis in multiple types of cancers such as breast cancer, liver cancer, and oral squamous cell carcinoma." (PMID 36983771, 2023). "LRP6’s expression is most often up-regulated in breast cancer tissue, and overexpression or knockdown of LRP6 causes or halts breast tumorigenesis." (PMID 35865469, 2022). "In cancer-associated fibroblast from mammary tumors, the stabilization of LRP6 at cell surface by DKK3 stimulates β-catenin and YAP/TAZ signals, promoting pro-tumorigenic functions such as ECM stiffening." (PMID 32850302, 2020). "By contrast, LRP5-deficient mice are viable, but develop Wnt1-induced mammary tumors much later than control mice, suggesting that LRP6 cannot compensate for LRP5 loss." (PMID 29854300, 2018). "Our results indicate that the anti-breast cancer activity of gigantol is associated with its inhibition of LRP6 activity." (PMID 29444668, 2018). "We found that increased expression of Lrp6 was associated with basal-like breast cancer (p = 1.8×10–4, p = 9.6×10–5)." (PMID 19503830, 2009). "Interestingly, IVM also decreased the expression of LRP6 and Axin1, proteins associated with activation at the Wnt receptor, in both endocrine-resistant breast cancer cell lines." (PMID 40569965, 2025). "High expression of low-density lipoprotein receptor-related protein 6 (LRP6), a key component of the Wnt/β-catenin signaling pathway, is reported to be associated with malignant potential in some solid tumors including breast cancer and hepatocellular carcinoma." (PMID 36983771, 2023). "We also found that human basal-like breast cancers are associated with increased Lrp6 expression, suggesting that these tumors may be enriched with Lrp6-expressing cells." (PMID 19503830, 2009). "In humans, increased Lrp6 expression is associated with basal-like breast cancer." (PMID 19503830, 2009). "Finally, an increased expression of Lrp6 is associated with human basal-like breast cancer." (PMID 19503830, 2009). "Kallistatin inhibits breast cancer cell proliferation, migration, and invasion by binding LRP6 to block Wnt/β-catenin signaling, with its heparin-binding site antagonizing Wnt3a-induced proliferation." (PMID 41561118, 2025). "Among these pathways, the p-ERK and p-AKT signaling in breast cancer, the LRP6/GSK3β/β-catenin axis in NPC, and the cytosolic fatty-acid-binding protein 7 (FABP7)/PPARγ axis in malignant gliomas have been reported." (PMID 40001923, 2025). "The combination of kallistatin with LRP6 blocks the activation of Wnt/β-catenin signaling pathway and thus inhibits angiogenesis, inflammtion and the growth of cancer cell in cultured human breast cancer cells." (PMID 41561118, 2025). "We previously evaluated the role of Lrp5 and Lrp6 in a mammary tumor model in which the ectopic expression of Wnt1 under the control of the MMTV promoter (MMTV-Wnt1) causes the rapid onset of mammary tumors." (PMID 40932232, 2025). "This aligns with results showing that silencing LRP6 decreased Wnt signaling, cell proliferation, and tumor growth in breast cancer." (PMID 40569965, 2025). "Regarding Wnt receptors, we observed that IVM reduced the expression of LRP6 in endocrine-resistant breast cancers." (PMID 40569965, 2025). "In Ren's paper 24, knocking down LRP5 or LRP6 promoted lung metastasis of breast cancer cells in a nude mouse model." (PMID 38706907, 2024). "Ren 24 has shown that in breast cancer, knockdown of LRP5 or LRP6 suppresses the Wnt signaling, but it increases lung metastasis in breast cancer cells in nude mice." (PMID 38706907, 2024).
breast cancer (continued). "LRP6 is an indispensable transmembrane receptor for Wnt and is overexpressed in several solid tumors, including colorectal, liver, and breast cancers, as well as pancreatic adenocarcinomas, in association with increased Wnt/β-catenin signaling." (PMID 36983771, 2023). "Another study showed that the Wnt co-receptor LRP6 is suppressed by silibinin and that its anticancer property is mediated by its influence on Wnt/LRP6 signaling in prostate and breast cancer cells." (PMID 37432240, 2023). "Among them, AptLRP6-A3 showed the highest affinity with LRP6-overexpressed human breast cancer cells." (PMID 37175248, 2023). "Pictilisb treatment increased LRP6 phosphorylation, β-catenin nuclear translocation and Wnt target gene expression in ER− human breast cancer cells." (PMID 37471270, 2023). "With regard to cancer, LRP6 expression is upregulated in several cancers, including breast cancer, hepatocellular carcinoma, colorectal cancer, and prostate cancer." (PMID 37175248, 2023). "Up regulation of the WNT LRP6 signaling pathway receptor has been noted in breast cancer cells, and its likely impact on the development of neoplastic processes has been demonstrated." (PMID 35453754, 2022). "Downregulation of LRP6 inhibits breast cancer tumorigenesis, whereas overexpression of LRP6 in the mouse mammary gland induces mammary hyperplasia." (PMID 35230971, 2022). "Clinical studies have shown that LRP6 is involved in various kinds of cancer, such as bladder and breast cancer." (PMID 35052459, 2022). "It has been reported that the recombinant Mesd protein and its C-terminal region peptide, two antagonists of LRP6, markedly suppressed Wnt/β-catenin signaling, cell proliferation and tumor growth in breast cancer." (PMID 34615853, 2021). "Multiple small molecular compounds (e.g., salinomycin, prodigiosin, silibinin, rottlerin, gigantol, and CDDO-Me) have been shown to inhibit the Wnt/β-catenin pathway and growth in breast cancer cells by acting on LRP6." (PMID 34615853, 2021). "More specifically, LRP6 is a well-known regulator of breast cancer: LRP6 expression is frequently upregulated in breast cancer tissue, and respective overexpression or knockdown of LRP6 induces or inhibits breast tumorigenesis." (PMID 34589484, 2021). "N-myc downstream regulated gene-1 protein (NDRG1) interacts with LRP6 and suppresses LRP6-mediated Wnt signaling activation, resulting in inhibition of breast cancer metastasis." (PMID 34589484, 2021). "Our results demonstrated that TMEM97 displayed oncogenic effects through regulation of LRP6-mediated Wnt signaling in breast cancer." (PMID 34615853, 2021). "The receptors Fz2, Fz3, Fz6, Fz7, and Fz10 as well as the co-receptor Lrp6 have also been reported to significantly increase in breast cancer and contribute to mesenchymal-like stemness, invasion, metastasis, and drug resistance." (PMID 33585487, 2021). "Knockdown of LRP6 significantly inhibited Wnt/β-catenin signaling and impaired cell proliferation and tumorigenesis in breast cancer." (PMID 34615853, 2021). "As a key co-receptor for Wnt/β-catenin signaling, LRP6 is a promising therapeutic target for breast cancer." (PMID 34615853, 2021). "Knockout of TMEM97 abrogated its oncogenic properties through downregulating LRP6-mediated Wnt signaling in breast cancer." (PMID 34615853, 2021). "LRP6 was shown to be significantly elevated in ~25% of breast cancers more so in TNBC than other types of breast cancer." (PMID 33488948, 2020). "Gigantol, a bibenzyl compound from orchid species, was also reported to inhibit Wnt/β-catenin signaling through down-regulation of phosphorylated LRP6 and cytosolic β-catenin in breast cancer cells." (PMID 33276800, 2020). "It is reported that LRP6 is up-regulated in various tumors, including colon cancer, breast cancer, as well as RB." (PMID 32669977, 2020).
breast cancer (continued). "The LRP6 co-receptor is also overexpressed in other tumors (colorectal, liver, and pancreatic cancers) and reducing LRP6 expression in these tumors, as well as in breast cancers, was proposed as a strategy for inhibiting tumor cell growth." (PMID 32210163, 2020). "In breast cancers, the members of the Wnt signaling family are rarely mutated: APC (1.3%), CTNNB1 (0.2%), AXIN1 (0.4%), LRP6 (0.7%), LGR5 (0.6%), TCF7L2 (0.3%), and FBXW7 (1.5%)." (PMID 32210163, 2020). "The LRP6 co-receptor is up-regulated in a subpopulation of breast cancers: LRP6 silencing in these cells reduces Wnt signaling and tumor cell proliferation." (PMID 32210163, 2020). "Together, these data suggested that Wnt/β-catenin signaling mediated through FZD8 and LRP6 plays a major role in human breast cancers, drug resistance and metastasis." (PMID 33488948, 2020). "The onset of metastasis decreases LRP6 levels in both murine and human serum from individuals with breast cancer." (PMID 33096815, 2020). "Sox9 is a poor prognostic indicator and is strongly associated with Wnt signaling via LRP6 (Low-density lipoprotein receptor-related protein 6) and TCF4 (Transcription Factor 4) in breast cancer." (PMID 31394796, 2019). "LRP6 has been reported in a broad panel of cancers including breast cancer, prostate cancer, hepatocellular carcinoma, and retinoblastoma." (PMID 31031810, 2019). "In another study, overexpressed LRP6 was also observed in a subpopulation of the human breast cancers suggesting that the Wnt signaling pathway activation by the overexpressed LRP6 was enough to induce the formation of breast cancer." (PMID 31031810, 2019). "This emphasizes the possibility that LRP6 can represent a potential therapeutic target for breast cancers." (PMID 31412666, 2019). "LRP6 silencing in breast cancer cell lines impairs proliferation, anchorage-independent cell growth and tumorigenesis in xenograft assays." (PMID 31412666, 2019). "Salinomycin is used to kill breast cancer stem and it was also reported to be the inhibitor of Wnt/β-catenin signaling by inducing LRP6 degradation." (PMID 31031810, 2019). "Gigantol inhibited Wnt/β-catenin signaling through downregulation of phosphorylated LRP6 and cytosolic β-catenin in breast cancer cells." (PMID 29444668, 2018). "LRP6 overexpression in the mouse mammary gland induces mammary hyperplasia, whereas LRP6 downregulation inhibits breast cancer tumorigenesis." (PMID 29854300, 2018). "LRP6 silencing in breast cancer cells reduced Wnt signaling, cell proliferation, and in vivo tumor growth." (PMID 29444668, 2018). "LRP5 DNA copy number (CN) in TNBC was higher than that in luminal A tumors only, but LRP6 DNA CN was higher in TNBC than in the other breast cancer subtypes." (PMID 29854300, 2018). "As LRP5 and LRP6 are coreceptors, we analyzed the expression of these two receptors in breast cancers and the effects of their depletion on the survival of breast cancer cells." (PMID 29854300, 2018). "Together, these results indicate that both LRP5 and LRP6 are overexpressed in TNBC relative to other breast cancer subtypes." (PMID 29854300, 2018). "Mesoderm development (Mesd), which binds directly to mature LRP5 and LRP6 on the cell surface and inhibits Wnt3a-induced Wnt signaling, decreases the growth of breast cancer tumors in vivo." (PMID 29854300, 2018). "HuR was shown to block Wnt5a signaling in human breast cancer by direct inhibition of translation, whereas in the intestinal epithelium HuR supports Wnt signaling by stabilizing LRP6 mRNA." (PMID 29364956, 2018). "We, therefore, analyzed the expression of both LRP5 and LRP6 in our set of breast cancer biopsy specimens." (PMID 29854300, 2018). "It inhibits Wnt/β-catenin signaling through downregulation of phosphorylated LRP6 and cytosolic β-catenin in breast cancer cells." (PMID 29444668, 2018). "LRP6 is an essential coreceptor in the Wnt/β-catenin signaling pathway and thus a potential therapeutic target in breast cancer treatments." (PMID 29444668, 2018).